MBD2 (methyl-CpG binding domain protein 2)
Diseases named in the same sentence as MBD2 in open-access papers (continued):
Sharing a sentence is not in itself a finding about the gene and the disease.
leukemia (continued). "Together, these data suggest that MBD2 deletion significantly impairs the colony-forming capacity of MLL-AF9-transformed cells and delays MLL-AF9-driven leukemia initiation." (PMID 34789717, 2021). "Strikingly, Mbd2−/− AML cells were much less aggressive than WT AML cells according to liquid culture and colony formation assays in vitro, which were applied to investigate the dynamic effect and colony-forming capacity of leukemia cells." (PMID 34789717, 2021). "Mbd2−/− and WT MLL-AF9-transformed cells obtained from the third generation of colonies were transplanted into mice irradiated with sublethal doses to induce leukemia." (PMID 34789717, 2021). "In summary, our data revealed that MBD2 deletion could delay the initiation and development of MLL-AF9 leukemia and promote LSC differentiation." (PMID 34789717, 2021). "We also performed homing assays to confirm that the homing potential of leukemia cells was not affected after MBD2 deletion." (PMID 34789717, 2021).
lung squamous cell carcinoma (2 papers, 2008 to 2024). "The high level of MBD2 expression had a significantly reduced risk for death only in male patients and in squamous cell lung carcinoma (SQLC) patients." (PMID 18414412, 2008).
lupus nephritis (2 papers, 2019 to 2025). Glomerulonephritis in the context of systemic lupus erythematosus. "Previous research identified elevated MBD2 expression in B cells associated with lupus nephritis." (PMID 40467564, 2025). "The suggestive associations detected between IRFs and epigenetic related factors: DNMT1 and MBD2, encouraged us to explore epigenetic aspects of lupus nephritis, as not only genetic changes may contribute to disease progress." (PMID 31507612, 2019).
melanoma (2 papers, 2013 to 2023). A malignant, usually aggressive tumor composed of atypical, neoplastic melanocytes. "Here, we report for the first time the characterization of the global melanoma CpG island methylome by MBD2-mediated pull-down, followed by next generation sequencing performed on samples from four different melanoma cell lines." (PMID 24129253, 2013). "To identify the highly methylated regions in the melanoma genome, we used methyl-CpG-binding protein (MBD2) to pull down methylated CpG islands of human melanoma cell lines and normal melanocytes (HEM-l), and the enriched sequences were subjected to deep-sequencing." (PMID 24129253, 2013). "Interestingly, consistent results were also observed in murine melanoma B16F10 cells, suggesting that altered MBD2 expression is a common feature adopted by tumor cells for metastasis." (PMID 37142578, 2023).
prostate tumor (2 papers, 2010 to 2015). "Taken together, these results indicate that the expression of Nrf2 is suppressed epigenetically by promoter methylation associated with MBD2 and histone modifications in the prostate tumor of TRAMP mice." (PMID 20062804, 2010). "Nrf2 expression was suppressed by methylation of certain CpG sites and this was accompanied by the recruitment of MBD2 and trimethyl-histone H3 (Lys9) to the Nrf2 gene promoter in prostate tumor of TRAMP mice." (PMID 20062804, 2010).
renal cell carcinoma (2 papers, 2019 to 2023). "It has been shown that GE can reactivate methylation-silenced tumor suppressor BTG3 gene by CpG demethylation and inhibition of DNMT and MBD2 activity in HEK- 293 renal cell carcinoma." (PMID 31030484, 2019).
squamous cell carcinoma (2 papers, 2001 to 2015). A carcinoma arising from squamous epithelial cells.
type 1 diabetes (2 papers, 2022 to 2025). "Furthermore, their research indicated that MBD2 functions as a repressor to maintain the homeostasis of the Th1 program in type 1 diabetes by regulating the STAT1–IFN-γ axis." (PMID 41258082, 2025). "Although derailed DNA methylation has long been recognized to trigger or promote autoimmune responses in type 1 diabetes (T1D), the exact role of MBD2 in T1D pathogenesis, however, remains poorly defined." (PMID 34420035, 2022). "Collectively, those data suggest that ectopic MBD2 expression represses the Th1 program, which has the potential to repress autoimmune responses in NOD.scid mice, thereby attenuating the development of type 1 diabetes." (PMID 34420035, 2022).
type 2 diabetes (2 papers, 2021 to 2026). "Mbd2 and Tnip1 have significant relationships between DNAm variation and insulin type 2 diabetes." (PMID 41432313, 2026).
viral infection (2 papers, 2016 to 2024). "The maturation of CD8+ T cell populations into effector and memory cells after acute viral infection is also directly affected by loss of MBD2, consistent with MBD2 regulating expression of surface markers and cytokines." (PMID 27303433, 2016). "Also, the localization of the MBD2/MBD3 NuRD Complex in the context of viral infection will provide new perspective on comprehending the cellular and molecular pathways influenced by HPV16 E6/E7 oncoproteins." (PMID 38790189, 2024).
acute myeloid leukemia (1 paper, 2024). Acute myeloid leukemia (AML) is a group of neoplasms arising from precursor cells committed to the myeloid cell-line differentiation. "MBD2 plays important roles in various tumors, especially acute myeloid leukemia; however, few reports on its role in the CCA exist." (PMID 39350229, 2024). "MBD2 has been reported to promote tumor progression in acute myeloid leukemia (AML), colorectal cancer, and medulloblastomas, but less research has been conducted in CCA." (PMID 39350229, 2024).
adenoma (1 paper, 2016). A neoplasm arising from the epithelium. "In this regard, it is significant that repression of Htra1 is mediated by MBD2, the deficiency of which we have previously shown to strongly suppress the majority of adenomas in the ApcMin+ mouse." (PMID 27388476, 2016). "The fact that adenomas do eventually form in this model suggests that MBD2-mediated suppression of target genes such as Htra1 may be relevant to a subset of lesions." (PMID 27388476, 2016).
atherosclerosis (1 paper, 2022). A disease characterized by the build-up of fatty material and calcium deposition in the arterial wall resulting in partial or complete occlusion of the arterial lumen. "Genetic alterations in MBD2 and UHRF1 have been linked to various cardiovascular pathologies such as atherosclerosis or arterial aneurism, which can trigger HF." (PMID 35453616, 2022).
Candida infection (1 paper, 2011). "In contrast to murine beta-defensin 1 (mBD1), which was not induced following infection in any of the mice, mBD2, -3, -and 4 all showed elevated expression in oral tissues following Candida infection in WT mice." (PMID 22174673, 2011).
cerebral infarction (1 paper, 2022). An ischemic condition of the brain, producing a persistent focal neurological deficit in the area of distribution of the cerebral arteries. "Confirming these changes, the MBD2/MBD3 ratio and neuronal cell death were significantly increased in the hippocampal CA1 area at 24 h after cerebral infarction, whereas there was no change in apoptosis or the MBD2/MBD3 ratio in the DG." (PMID 36142283, 2022).
chronic hepatitis B (1 paper, 2019).
colon adenomatous polyps (1 paper, 2008). "However, Apc(Min/+) mice (a mouse model for colon adenomatous polyps) lacking MBD2 show up to 10 times reduced intestinal tumorigenesis and more localised tumours than those Apc(Min/+) MBD2+/+." (PMID 18542062, 2008).
embryonal carcinoma (1 paper, 2022). A non-seminomatous malignant germ cell tumor characterized by the presence of large germ cells with abundant cytoplasm resembling epithelial cells, geographic necrosis, high mitotic activity, and pseudoglandular and pseudopapillary structures formation. "Several studies have shown potential interaction between SOX2 and MTA1/2/3, MBD2, GATAD2A/B, and HDAC1/2 in different cell lines, including embryonic stem cells, neural stem cells, and embryonal carcinoma cells." (PMID 35615634, 2022).
fracture (1 paper, 2024). "Previous studies have extensively explored the role of macrophages in fracture infection and the function of MBD2 in regulating cellular function, but many aspects of the specific molecular mechanisms remain unclear." (PMID 39198853, 2024).
Glucose intolerance (1 paper, 2026). Glucose intolerance (GI) can be defined as dysglycemia that comprises both prediabetes and diabetes. "The predictor variables can be considered in three groups: those with insulin and glucose intolerance (Mbd2, Tnip1, Itgb4, and Iffo2), those with BMR (1010001N08RiK and Clvs2), and those associated with Tb (Calb2)." (PMID 41432313, 2026).
head and neck squamous cell carcinoma (1 paper, 2024). A squamous cell carcinoma that arises from any of the following anatomic sites: lip and oral cavity, nasal cavity, paranasal sinuses, pharynx, larynx, and salivary glands. "The molecular mechanisms of MBD2 in head and neck squamous cell carcinoma (HNSCC) remain insufficiently characterized." (PMID 39676597, 2024).
Insulin resistance (1 paper, 2025). Increased resistance towards insulin, that is, diminished effectiveness of insulin in reducing blood glucose levels. "For example, MBD2 expression is significantly reduced in omental adipose tissue of IR individuals compared to IS individuals, suggesting a potential loss of epigenetic regulation in key stromal cell types associated with insulin resistance." (PMID 41030849, 2025).
intestinal tumours (1 paper, 2018). "Potentially, the intestinal tumour resistance of the Mbd2−/− mouse is due to an enhanced anti‐tumourigenic Th1/Ifng response, a loss of Mbd2 epigenetic regulation within the intestinal epithelia or a combination of both." (PMID 29603746, 2018). "To achieve this, we examined MBD2 expression in a panel of human intestinal tumours (TNM stage I–IV, N = 7 per stage)." (PMID 29603746, 2018).
ischemia (1 paper, 2012). A hypoperfusion of the BLOOD through an organ or tissue caused by a PATHOLOGIC CONSTRICTION or obstruction of its BLOOD VESSELS, or an absence of BLOOD CIRCULATION. "It has been reported that MBD2 was induced in hippocampus within few hours post-ischemia and maintained at high levels for several days." (PMID 23285140, 2012).
ischemic stroke (1 paper, 2022). A stroke disorder caused by obstruction of blood flow to the brain, due to thrombotic (local blood clot formation) or embolic (due to a blood clot or other material traveling from another site) event. "The effect of DNA methylation on endothelial function in ischemic stroke was also analyzed on the basis of the regulation of MBD2, an interpreter of the information-encoding DNA methylome." (PMID 36142283, 2022). "Overall, these findings indicate that inhibition of MBD2 activity has the potential to improve angiogenesis, which is a major mechanism in neural recovery after ischemic stroke." (PMID 36142283, 2022).
lupus-like syndrome (1 paper, 2019). "As part of the NuRD complex, MBD2 is involved in B and T cell maturation, which might explain that MBD2 KO mice develop lupus-like syndrome." (PMID 31718084, 2019).
multiple sclerosis (1 paper, 2025). A progressive autoimmune disorder affecting the central nervous system resulting in demyelination. "In rheumatoid arthritis and multiple sclerosis, patients exhibit global DNA hypomethylation compared to healthy individuals, accompanied by elevated mRNA expression levels of MBD2 and DNMT1." (PMID 40533455, 2025).
myeloid leukemia (1 paper, 2021). A clonal proliferation of myeloid cells and their precursors in the bone marrow, peripheral blood, and spleen. "MBD2 expression was negatively correlated with CDKN1C expression in clinical myeloid leukemia samples." (PMID 34789717, 2021). "Recipient mice from both the Mbd2−/− group and the WT group developed AML, and the GFP+ cells were shown to be B220−CD3−Mac-1+ by flow cytometric analysis, suggesting the construction of a myeloid leukemia model." (PMID 34789717, 2021).
neuroblastoma (1 paper, 2022). Neuroblastoma (NB) is the most common solid, extracranial childhood tumor. "MBD2 has been proven to significantly inhibit the expression of telomerase reverse transcriptase (TERT) via binding the hypermethylated region of the TERT promoter in liver, breast, cervical, and neuroblastoma cell lines." (PMID 35051313, 2022).
oral squamous cell carcinoma (1 paper, 2021). "Downregulation of miR221 inhibits cell migration and invasion through targeting methyl-CpG binding domain protein 2 in human oral squamous cell carcinoma cells." (PMID 34340715, 2021).
ovarian carcinoma (1 paper, 2008). A malignant neoplasm originating from the surface ovarian epithelium. "It was found that the methyl-CpG-binding domain protein 2 (MBD2) was recruited to CpG sites and silenced the CLDN4 gene in ovarian cancer cell lines without interfering with SP1 binding." (PMID 18423053, 2008).
prostate adenocarcinoma (1 paper, 2023). "In silico RNA sequencing of prostate adenocarcinoma (PRAD) TCGA analysis demonstrated upregulation of DNMT3B, DNMT1, and MBD2 in tumors (n = 497) compared to normal (n = 52) samples, suggesting a global increase in DNA methylation, which might be associated with gene-specific downregulation." (PMID 38201944, 2023).
retinal degeneration (1 paper, 2023). Degeneration of the retina. "Concerning DP, MBD2 was involved in the formation of the eye, interacting both with HK2 and HIF1A, while PIWIL4 displayed an interaction with DICER1, which was involved in retinal degeneration." (PMID 37359372, 2023).
Salmonella Infections (1 paper, 2023). Infections with bacteria of the genus SALMONELLA. "The most important TF for predicting the response to Salmonella infection was IRF8, followed by MBD2 and ZBT14." (PMID 37073532, 2023).
salpingitis (1 paper, 2025). Acute or chronic inflammation of the fallopian tube. "In this study, the effects of E2 and P4 on the expression of IL-1β, TNF-α, IL-10, and mBD-2 in LPS-stimulated fallopian tube epithelial cells, as well as the potential mediation of postinjury salpingitis through the NF-κB, MAPK, and PI3K/Akt pathways, were investigated." (PMID 40604711, 2025). "Estrogen and progesterone can protect against LPS-induced mouse salpingitis by inhibiting the activation of the NF-κB, MAPK, and PI3K/Akt signaling pathways and suppressing the expression of the inflammatory factors IL-1β, TNF-α, IL-10, and mBD-2." (PMID 40604711, 2025).
Sjogren syndrome (1 paper, 2022). An autoimmune disorder in which immune cells attack and destroy the glands that produce tears and saliva. "It was interestingly noted that Mbd2−/− NOD mice exhibited increased infiltration of lymphocytes in the salivary gland, a feature prior to the development of Sjogren’s syndrome, but no evident inflammatory infiltration was observed in the colon, lung, kidney, liver, or heart." (PMID 34420035, 2022).
Splenomegaly (1 paper, 2022). Abnormal increased size of the spleen. "The Mbd2−/− NOD mice exhibited splenomegaly and pancreatic lymphadenopathy, suggesting a more severe autoimmune response." (PMID 34420035, 2022).
staphylococcus aureus infection (1 paper, 2024). An infectious process in which the bacteria Staphylococcus aureus is present. "Furthermore, the KEGG enrichment analysis revealed MBD2’s involvement in the “Staphylococcus aureus infection” signaling pathway." (PMID 39198853, 2024).
status epilepticus (1 paper, 2026). Status epilepticus is defined as a continuous seizure lasting more than 30 min, or two or more seizures without full recovery of consciousness between any of them. "In wild-type mice, pilocarpine-induced status epilepticus increases PYK2 and MBD2 nuclear localization in hippocampal neurons, especially in CA3." (PMID 42020370, 2026).
Stroke (1 paper, 2022). Sudden impairment of blood flow to a part of the brain due to occlusion or rupture of an artery to the brain.
thyroid cancer (1 paper, 2017). "Although gene body methylation has been revealed to play a crucial role in METTL7A transcriptional regulation, the enrichment of RNA pol II and MBD2 to modulate METTL7A transcriptional change only occurs in thyroid cancer cells, however, the mechanism behind this is still unknown." (PMID 28416772, 2017). "Overall, we revealed that EZH2 interacted with the CpG site at the gene body of METTL7A and was responsible for MBD2 recruitment as well as RNA pol II rejection, which leads to METTL7A silencing in thyroid cancer." (PMID 28416772, 2017). "Interestingly, the presence of declining MBD2 whereas increased RNA pol II enrichment in CpG mutant METTL7A template compared to the wild type one was observed in thyroid cancer cells but not in normal cells." (PMID 28416772, 2017).
tuberculosis (1 paper, 2019). A chronic, recurrent infection caused by the bacterium Mycobacterium tuberculosis. "Although the role of MBD2 in tuberculosis is undefined, previous study reported that mycobacterial proteins could modify gene methylation in mammalian host tissues." (PMID 30984625, 2019).